NOTCH4 (notch receptor 4)
Description:
Functions as a receptor for membrane-bound ligands Jagged1, Jagged2 and Delta1 to regulate cell-fate determination. Upon ligand activation through the released notch intracellular domain (NICD) it forms a transcriptional activator complex with RBPJ/RBPSUH and activates genes of the enhancer of split locus. Affects the implementation of differentiation, proliferation and apoptotic programs. May regulate branching morphogenesis in the developing vascular system (By similarity).
Synonyms: INT3
Tractability: Small molecule: a structure with a bound ligand is known. Antibody: its Gene Ontology location is reachable by antibodies, with high confidence; UniProt places it where antibodies can reach, with medium confidence; UniProt predicts a signal peptide or a membrane-spanning region. PROTAC: a small molecule that binds it is known.
Target class: Membrane receptor
Safety:
Unwanted effects reported when the protein is acted on. In parentheses: how it was acted on, where the effect was seen, and who reports it.
severe cutaneous adverse reactions (SCAR) (source: ClinPGx)
Gene: Protein-coding gene on chromosome 6 (32,194,843 to 32,224,111, reverse strand). Ensembl gene ENSG00000204301.
Subcellular location: Cell membrane; Nucleus (Notch 4 intracellular domain)
Pathways (Reactome):
Signal Transduction: NOTCH4 Activation and Transmission of Signal to the Nucleus; NOTCH4 Intracellular Domain Regulates Transcription; Negative regulation of NOTCH4 signaling; Pre-NOTCH Processing in Golgi; Pre-NOTCH Processing in the Endoplasmic Reticulum; Pre-NOTCH Transcription and Translation
Disease: Defective LFNG causes SCDO3
Gene expression (Transcription): Notch-HLH transcription pathway
Gene Ontology:
Molecular function: protein binding; transcription coactivator activity; calcium ion binding; Notch binding; signaling receptor activity
Biological process: epithelial to mesenchymal transition; mammary gland development; negative regulation of cell adhesion molecule production; negative regulation of cell-cell adhesion mediated by cadherin; negative regulation of transcription by RNA polymerase II; positive regulation of smooth muscle cell differentiation; positive regulation of transcription by RNA polymerase II; branching involved in blood vessel morphogenesis; cell differentiation; cell fate determination; hemopoiesis; morphogenesis of a branching structure; negative regulation of cell differentiation; negative regulation of endothelial cell differentiation; positive regulation of DNA-templated transcription; positive regulation of transcription of Notch receptor target; vasculature development; cell development; Notch signaling pathway; positive regulation of developmental process; regulation of cell differentiation; regulation of developmental process; regulation of DNA-templated transcription; tissue development
Cellular component: cell surface; cytosol; endoplasmic reticulum membrane; extracellular region; Golgi membrane; nucleoplasm; nucleus; plasma membrane; membrane
Genetic constraint (gnomAD): Loss-of-function variants: 137 observed, 182.36 expected, observed/expected ratio (o/e) 0.75, 90% interval 0.65 to 0.87. The upper end of that interval is the gene's LOEUF score, 0.87, which puts it in group 3 of 6, group 1 being the genes least tolerant of losing a copy. Missense variants: 2,285 observed, 2,589.1 expected, observed/expected ratio (o/e) 0.88, 90% interval 0.85 to 0.91. Synonymous variants: 941 observed, 1,022.2 expected, observed/expected ratio (o/e) 0.92, 90% interval 0.87 to 0.97.
Homologues: Orthologues: chimpanzee NOTCH4 (99% identical), macaque NOTCH4 (97% identical), pig NOTCH4 (87% identical), rat Notch4 (76% identical), zebrafish jag2b (18% identical), zebrafish jag1b (17% identical), zebrafish jag1a (17% identical), zebrafish jag2a (17% identical), Caenorhabditis elegans F55H12.3 (13% identical), Caenorhabditis elegans fbn-1 (12% identical), tropical clawed frog muc4 (11% identical), zebrafish si:ch73-105b23.1 (10% identical), and 6 more. Paralogues in human: JAG2 (18% identical), JAG1 (18% identical), DLL1 (10% identical), DLL4 (9% identical), DNER (8% identical).
Diseases named in the same sentence as NOTCH4 in open-access papers:
NOTCH4 is named in the same sentence as 187 diseases in open-access papers, as found by Europe PMC text mining. Sharing a sentence is not in itself a finding about the gene and the disease. The quoted sentences say what the papers report.
breast cancer (101 papers, 2004 to 2026). A primary or metastatic malignant neoplasm involving the breast. "Using endothelium-specific, ribosome-associated mRNA sequencing to evaluate expression changes in a mouse breast cancer model treated with 6-3-A6, we determined that Notch4 inhibition alters tumor endothelial pathways associated with vascular function." (PMID 38984877, 2024). "The vertebrate homologues Notch1 and Notch4 are involved in normal development of mammary glands and their mutated variations are associated with the development of mammary tumors in the mouse." (PMID 34587981, 2021). "A comparison of human breast cancer cell lines, which differ in the levels of endogenous Notch4, implicated the protein in regulating susceptibility to apoptosis triggered by genomic damage." (PMID 32123583, 2020). "Notch inhibitors have already demonstrated activity in combination with tamoxifen, and Notch 4, in particular, has been implicated as a viable target to prevent metastasis in tamoxifen-resistance breast cancer." (PMID 30975104, 2019). "Given that Notch4 and Notch3 are expressed at higher levels in poorly differentiated basal breast cancers it will be important to elucidate the association of different Notch pathways with Tregs during cancer formation." (PMID 30061899, 2018). "Notch4 and Notch3 are expressed at higher levels in poorly differentiated basal breast cancers and are associated with poor overall survival." (PMID 30061899, 2018). "The aberrant activation of Notch-4 signaling pathway has been proven to be associated with the development and progression of breast cancers." (PMID 29057904, 2017). "The specific roles and the underlying mechanisms of Notch-4 signaling pathway on the malignant behavior of breast cancer are poorly understood." (PMID 29057904, 2017). "Activated Notch4 is closely associated with the promotion of estrogen-independence and chemotherapy resistance in breast cancer cells." (PMID 27344175, 2016). "For instance, while studies demonstrated that the truncated form of Notch4 has a causative role in the development of mammary tumors in animal models, others reported a possible oncogenic role of Notch1 overexpression in human breast cancer tissues." (PMID 27929540, 2016). "In humans, Notch4 expression appears to be associated with breast cancer stem cells and endocrine resistance." (PMID 25740432, 2015). "Expression of Notch 4 is associated with the basal-like subtype of breast cancer." (PMID 37726449, 2024). "Moreover, NOTCH4 downregulation is linked to suppressed proliferation and induced apoptosis of Erbb2-negative breast cancer cell lines." (PMID 35136410, 2022). "Supporting this, mutation of ER in breast cancer stem cells induces Notch4 activity." (PMID 34295896, 2021). "Notch4 signaling promotes breast cancer cell survival in response to diverse treatment modalities and is implicated in poor prognosis and high risk of relapse in breast cancer patients." (PMID 32123583, 2020). "The first evidence that Notch4 could function as a protooncogene was associated with mouse mammary tumors which showed integration of the mouse mammary tumors virus (MMTV) into the Notch4 locus." (PMID 31379945, 2019). "Interestingly, some well investigated proteins associated with breast cancer were identified, including notch-4, jagged-1 and CD34." (PMID 29899833, 2018). "Since Notch4 is predominantly expressed in the vascular endothelium in mice, we therefore used orthotopic transplantation of mouse mammary carcinoma cells wild type for Notch4 into syngeneic Notch4-deficient hosts to test the importance of Notch4 in tumor angiogenesis." (PMID 23601498, 2013). "Several recent studies have reported that mutations in NOTCH3 and NOTCH4 may cause breast cancer." (PMID 28977883, 2017). "Among the key findings was the overexpression of NOTCH4, a Notch receptor known to promote stemness, invasiveness, and treatment resistance, particularly in aggressive breast cancer subtypes." (PMID 41463075, 2025).
breast cancer (continued). "High expression of Nicastrin and Notch4 in breast cancer cells can induce the acquisition of EMT phenotype and tamoxifen resistance." (PMID 41211430, 2025). "Interrogation of a public database of 26 human breast cancer samples shows that Notch4 is expressed primarily in ECs in tumors and further enriched in tip-like endothelial clusters." (PMID 38984877, 2024). "A first-in-class anti-Notch4 agent, E7011, demonstrates strong antitumor effects in murine tumor models including breast carcinoma." (PMID 38984877, 2024). "One of these studies assesses the intranuclear and intranucleolar localisation of Notch4 in breast cancer cells." (PMID 37108670, 2023). "Collectively, these results indicate that silencing Notch4 in TNBC cells suppresses breast cancer migration in vitro via the location of Vimentin expression." (PMID 37149651, 2023). "Previous research showed that Notch4 played a role in maintaining quiescent mesenchymal-like breast cancer stem cells and promoting epithelial-mesenchymal transition in TNBC cells, indicating that Notch4 is a potential therapeutic target for TNBC." (PMID 37149651, 2023). "As expected, overexpression of Notch4 in M231shN4C shifted cobblestone-like morphology to the slightly spindle-shaped morphology, suggesting that Notch4 enhanced breast cancer metastasis." (PMID 37149651, 2023). "Notch4, a member of the Notch receptor family in mammals, was originally identified as a viral oncogene Int3 in mice, and is involved in the initiation of mammary tumors." (PMID 36817473, 2023). "Our results are consistent to previous reports that suggest Notch4 possesses tumor-promoting functions in other cancer types, including head and neck cancer, breast cancer, melanoma, and gastric cancer." (PMID 36970723, 2022). "Soon after, it was noted that viral integrations of mouse mammary tumor virus into the mouse Notch4 locus led to the development of mammary tumors as a consequence of the viral promoter driving expression of a truncated Notch4 ICD-like moiety." (PMID 35682918, 2022). "In breast cancer, NOTCH4 is predominantly expressed in the Her2 subtype, and the expression is also discovered to be associated with bad prognostic factors." (PMID 36313438, 2022). "Concerning Notch4 in breast cancer, it is required for CSC maintenance, and its high levels have been documented in patient samples." (PMID 34680255, 2021). "In breast cancer patients with low level of Notch-4, the overall surveillance is higher (81.8% at 2 years after treatment) compared to patients with high level of Notch-4 (63.2%)." (PMID 34337053, 2021). "In line with its connection to endocrine therapy resistance, Notch4 appears to be the most important of the Notch receptors in breast cancer stem cells." (PMID 34295896, 2021). "In accordance with this, NOTCH1 and NOTCH4 were found to be expressed in a subset of breast cancer cells where their expression also correlated with poor prognostic factors." (PMID 33530306, 2021). "But the expression of Notch4 was required for tumor onset and early tumor perfusion in a mouse model of breast cancer, despite the phenomenon that the final tumor size was similar between tumors grown in wild type and Notch4-null hosts." (PMID 34746000, 2021). "NOTCH4/STAT3 crosstalk is also important for epithelial-mesenchymal transition of breast cancer cells and NOTCH inhibition reduced the level of activated STAT3." (PMID 33530306, 2021). "The mechanism of Notch4-mediated resistance to hormonal therapy of breast cancer is worth mentioning." (PMID 34680255, 2021). "Our further analysis of public database indicated that higher expression level of NOTCH4 significantly correlated with poorer overall survival of breast cancer patients." (PMID 32104513, 2020). "The NOTCH family genes, including NOTCH1, NOTCH2, NOTCH3, and NOTCH4, are highly expressed in breast cancer patients." (PMID 33324444, 2020).
breast cancer (continued). "Notch 4 is significantly overexpressed in TNBC and HER2+ breast cancer compared to other breast cancer subtypes, and it was associated with a more aggressive clinical phenotype as well as poorer OS in luminal breast cancer patients." (PMID 32575680, 2020). "In vitro studies using ER+ breast cancer lines provided the initial evidence that Notch activation contributes to resistance to endocrine therapy and that targeting Notch1 or Notch4 by using genetic or pharmacologic means reversed this resistance." (PMID 33003540, 2020). "In breast cancer cells, Notch1 or Notch4 can promote the expression of Slug by activating the Slug promoter." (PMID 32636747, 2020). "We determined the mRNA level of NOTCH receptors in breast cancer cells and observed that NOTCH4 was highly expressed in TNBC cells, implying an important role of NOTCH4 in TNBC." (PMID 32104513, 2020). "Recently, a study reported that Notch4/STAT3 crosstalk is important for EMT in breast cancer, and IHC assays showed that Jagged1 and STAT3 protein were both expressed in the tissues of the cisplatin‐resistant group and the cisplatin responsive group." (PMID 30993885, 2019). "The treatment with an orally active GSI inhibitor (RO4929097) reverted the phenotype, thus inhibiting primary tumor growth, reducing the number of metastatic lung nodules, and finally confirming the contribution of Notch4 during mammary tumor progression." (PMID 31379945, 2019). "Notch4 was first discovered as one of the integration sites ofmouse mammary tumour virus (MMTV), which results incontinuous expression of the Notch4 intracellular domainand mammary tumour formation." (PMID 30930637, 2019). "The coordination of these genes in Notch signaling has been thoroughly reviewed and Notch4 in particular has been shown to maintain breast cancer stem cells." (PMID 30484104, 2019). "Notch4 thus promotes estrogen-independent, endocrine therapy resistant growth of breast cancer cell lines possibly through a Notch4/STAT3/EMT regulated axis." (PMID 30515368, 2018). "In this role, Notch4 appears to be particularly important, as knockdown of Notch4 has a much more significant effect on breast cancer stem cell numbers than Notch1 knockdown." (PMID 26880941, 2016). "This study also revealed that the inhibitory effect of withaferin-A on breast cancer stem cells proliferation was partly mediated through cleavage of Notch-4." (PMID 26959007, 2016). "While the compound attenuated the activation of Notch-1 in colon cancer and human breast cancer cells, it activates the cleavage of Notch-2 and Notch-4 in human breast cancer (MDA-MB-231) cells." (PMID 26959007, 2016). "The Notch4 isoform, which is specific to mammals, was originally identified as a viral oncogene in mice, Int3, able to initiate mammary tumors." (PMID 25740432, 2015). "show that combining standard anti-estrogen therapies with anti-Notch4 drugs targeting breast cancer stem cells should improve treatment of ER+ breast cancer patients by preventing relapse due to therapy resistance." (PMID 26387946, 2015). "Evidence also exists that Notch4 is essential for the maintenance of the elusive breast cancer stem cells." (PMID 25740432, 2015). "The first evidence that Notch receptors are breast oncogenes was provided in mouse studies in which active forms of Notch1 or Notch4 formed spontaneous murine mammary tumors in vivo." (PMID 25645291, 2015). "Our finding suggest that targeting Nicastrin and/or Notch4 warrants further clinical evaluation as valid therapeutic strategies in endocrine-resistant breast cancer." (PMID 24919951, 2014). "Recently, a functional crosstalk between PKCα and Notch4 has been reported in endocrine-resistant breast cancer cells." (PMID 24919951, 2014). "It was previously reported that Ki67 is found in 90% of TNBC and its expression correlates to Notch4, which is induced by Notch1 in breast cancer samples." (PMID 24716804, 2014).